CRP (C-reactive protein)
Diseases named in the same sentence as CRP in open-access papers (continued):
Sharing a sentence is not in itself a finding about the gene and the disease.
endothelial dysfunction (continued). "The findings suggest that inflammatory biomarkers like CRP may reflect generalized inflammation without capturing localized processes, such as endothelial dysfunction and venous remodeling, that are critical to PTS." (PMID 40226620, 2025). "Thus, the coexistence of high CRP and CA125 may reflect a clinical state of persistent inflammation, endothelial dysfunction, and advanced serosal congestion." (PMID 40894478, 2025). "Interestingly, the possible involvement of CRP in the development of endothelial dysfunction in the aorta has not been studied in SHR-CRP rats so far." (PMID 38627621, 2024). "Also, reductions in the C-reactive protein (CRP), TNF-α, and IL-6 further illustrate the anti-inflammatory properties of GLP-1RAs, which play a crucial role in mitigating ischemia–reperfusion injury and endothelial dysfunction." (PMID 38675485, 2024). "Fourth, there is a limitation to explaining the mechanism of an independent role of platelets in microvascular endothelial dysfunction due to a lack of data about thrombopoietin, C-reactive protein, pro-inflammatory cytokines, renin, angiotensin II, or aldosterone in this study." (PMID 38248790, 2024). "Periodontal disease can lead to elevated levels of inflammatory markers such as C-reactive protein (CRP), interleukin-6 (IL-6), and tumor necrosis factor-alpha (TNF-α), which may contribute to endothelial dysfunction and impaired placental blood flow, thereby increasing the risk of pre-eclampsia." (PMID 39401230, 2024). "While purified native human pCRP itself is described not to be pro‐inflammatory when injected into healthy individuals, earlier studies using recombinant human CRP reported endothelial dysfunction and augmented pro‐coagulant responses, which were not attributed to potential LPS contaminations." (PMID 36468184, 2023). "Furthermore, the BMI was associated with inflammatory markers (CRP, SAA) and non-HDLc levels; it correlated with endothelial dysfunction, but not with other cardiovascular measurements (blood pressure, resting heart rate and PWV)." (PMID 31492166, 2019). "The statistical correlation between inflammation reflected by C-reactive protein and TER, previously demonstrated in patients undergoing major abdominal surgery, was confirmed in this study, and is in line with previous reports on groups of patients with endothelial dysfunction." (PMID 29880012, 2018). "In this setting, it is not unusual to find also other changes due to endothelial dysfunction, which might explain the transient microangiopathic hemolysis and increased CRP of our case." (PMID 27389397, 2016). "Also measured were: C reactive protein (CRP), endothelial dysfunction (sVCAM and sICAM), prothrombotic activity (PAI-1), lipid profile (triglycerides, cholesterol, HDLc, LDLc, Apo-A1, and Apo-B100), glycated haemoglobin and lipid peroxidation (LDL-ox and MDA values)." (PMID 24083393, 2013). "On the other hand, the elevated levels of CRP and the pro-inflammatory cytokines, TNF-α and IL-6, reflect the presence of low-grade inflammation in obese subjects with IR that could contribute to endothelial dysfunction." (PMID 24138787, 2013). "Furthermore, certain inflammatory parameters such as C-reactive protein were not measured in the study, which might provide more information about the pathophysiology of endothelial dysfunction and its relationship with OPG in patients with HTN." (PMID 37893512, 2023). "Through further and concomitant secretion of CRP, NO, and several related inflammatory mediators, this mechanism could determine an additional negative stimulus to further develop CVD and related endothelial dysfunction in predisposed subjects." (PMID 37814162, 2023). "However, the association observed between PTX-3 and CKD is independent of inflammatory and endothelial dysfunction biomarker C-reactive protein in our study, suggesting that PTX-3 might play a role in pathogenesis of CKD via an additional pathway such as abnormal angiogenesis." (PMID 29783932, 2018).
endothelial dysfunction (continued). "On the other hand, our study did not confirm a beneficial effect of lowering the markers of endothelial dysfunction (serum ADMA), systemic inflammation (high sensitivity-CRP) and vascular stiffness (ABI) after eight weeks of febuxostat treatments among patients with CKD stages III to IV patients." (PMID 37596359, 2023). "Patients with elevated CRP but normal CA125 may represent a subset of individuals in which systemic inflammation is present, but the pathophysiological processes that involve volume overload or endothelial dysfunction are not as pronounced." (PMID 40894478, 2025). "Additionally, patients with PCOS may also have elevated levels of non-traditional factors, including C-reactive protein (CRP), carotid intima-media thickness (IMT), coronary artery calcification (CAC), as well as endothelial dysfunction, which raises the likelihood of complications from CVD." (PMID 40277055, 2025).
rheumatoid arthritis (615 papers, 2005 to 2026). A chronic, systemic autoimmune disorder characterized by inflammation in the synovial membranes and articular surfaces. "Consistently, previous studies have found that these three metabolites are closely associated with rheumatoid arthritis, IL-6, C-reactive protein, and other inflammatory markers." (PMID 39997739, 2025). "We performed a PubMed search using keywords such as rheumatoid arthritis, cardiovascular risk, inflammation, C-reactive protein, interleukin-6, microvascular disease, and carotid ultrasound." (PMID 41010664, 2025). "Evidence in autoimmune disorders, such as rheumatoid arthritis (RA), has been linked to reductions in disease severity, enhanced joint function, and lower C‐reactive protein (CRP)." (PMID 40901658, 2025). "Due to its effect on inflammatory markers such as c-peptide, estrone, total estradiol, free estradiol, leptin, CRP, IL-6, sTNF-2, and total adiponectin, caffeinated coffee consumption was linked to an increased risk of rheumatoid arthritis." (PMID 39596082, 2024). "Association between C-reactive protein (CRP) levels in rheumatoid arthritis patients and healthy controls using the chi-square test." (PMID 39092366, 2024). "We excluded 105 patients diagnosed with any disease that can cause elevated CRP, such as infections, acute or chronic inflammatory diseases such as rheumatoid arthritis, gout, Crohn’s disease, autoimmune disorders, cancers, or recent trauma." (PMID 38983990, 2024). "This MR study validated the genetic instrument for IL-1RA by examining the associations of genetically proxied IL-1RA levels with CRP levels and rheumatoid arthritis." (PMID 37781392, 2023). "Associations of systemic chemerin with CRP were observed in different patient cohorts such as rheumatoid arthritis, systemic sclerosis and colorectal cancer." (PMID 37509420, 2023). "It is generally accepted that inflammation measured with C-reactive protein is associated with rheumatoid arthritis more often than with the two other RDs investigated in this study." (PMID 35407647, 2022). "Recently, in patients with rheumatoid arthritis, serum CRP levels have been positively associated with Cu levels but not with Zn and Mn levels." (PMID 35741335, 2022). "Another recent study conducted in Italy also showed that exposure to high levels of air pollution including PM2.5 was correlated with increased C-reactive protein levels, as well as a higher risk of developing flares of rheumatoid arthritis." (PMID 35742255, 2022). "Two studies conducted in England and in Sweden showed that the implementation of MD in patients with rheumatoid arthritis was mainly associated with an improved perception of pain and disease activity but also clinical indices (e.g., CRP)." (PMID 34416917, 2021). "(most-likely H. parainfluenzae) was negatively associated with the level of serum C-reactive protein, an inflammatory marker, in rheumatoid arthritis (RA) patients, which complements the findings of the present study." (PMID 33707430, 2021). "Increased levels of CRP in blood are associated with almost all types of inflammatory disorders, especially in patients suffering from rheumatoid arthritis." (PMID 33224258, 2020). "TJC, CRP and RF-IgG screened out by our study were reported to associate with disease activity, prognosis, efficacy of rheumatoid arthritis or JIA." (PMID 31649533, 2019). "Our finding is in accordance with a previous study where a strong association of YKL-40 with CRP was described in patients with rheumatoid arthritis." (PMID 27612200, 2016). "Serum sRAGE levels in 138 patients suffering from rheumatoid arthritis were negatively associated with serum levels of C-reactive protein (CRP) and history of vasculitis." (PMID 26854151, 2015). "It is well known that the association between CRP levels and inflammation is lower in SpA than in rheumatoid arthritis." (PMID 23657512, 2013).
rheumatoid arthritis (continued). "Szalai's group examined the effect of both CRP deficiency (CRP−/− mice) and overexpression (CRPtg) mice on the course of collagen-induced arthritis a model for human rheumatoid arthritis." (PMID 24167754, 2013). "Although some studies have looked at the CRP gene variant response, few, if any, studies have examined the CRP gene variant response in the context of chronic inflammation, such as in rheumatoid arthritis." (PMID 20877716, 2010). "A genetic association study by Timothy Vyse and colleagues suggests that there is a significant association between CRP variants and acute-phase serum CRP concentrations in patients with rheumatoid arthritis, including those with chronic inflammation." (PMID 20877716, 2010). "In this paper we study the association between genetic variants at the CRP locus and acute-phase CRP in patients with chronic active inflammation due to rheumatoid arthritis." (PMID 20877716, 2010). "This is the first study to demonstrate that increased mean CRP observed throughout the disease process is associated with accelerated progression to total joint replacement for patients with rheumatoid arthritis." (PMID 18983663, 2008). "Beyond cardiometabolic disease, increased intake of UPF was associated with to the onset of rheumatoid arthritis in the U.K. Biobank, with partial mediation through CRP, high-density lipoprotein cholesterol, white blood cell count, and composite inflammatory indices." (PMID 41010537, 2025). "Additionally, CRP has shown strong predictive performance in forecasting the occurrence of rheumatoid arthritis-associated PF." (PMID 40546283, 2025). "Interestingly, the use of tocilizumab, an anti-IL-6 therapy, has been shown to be associated with a rapid QTc shortening in patients with rheumatoid arthritis, which was correlated with the decrease in both CRP and tumor necrosis factor (TNF)-α levels." (PMID 38337348, 2024). "Moreover, in the presence of additional infection sites or rheumatoid arthritis, elevated CRP values are difficult to attribute to a specific cause." (PMID 39727803, 2024). "Furthermore, autoimmune diseases such as systemic sclerosis and rheumatoid arthritis have also been linked to increased CRP levels." (PMID 38419270, 2024). "CRP may be a useful acute marker of inflammation associated with IVDD; however, it should be noted that CRP plasma levels are also increased in rheumatoid arthritis, infection, cancer, and tissue trauma." (PMID 37756062, 2023). "Univariate and logistic regression analyses of parameters recorded at hospital admission showed that age older than 72.5 years, rheumatoid arthritis, creatinine > 1.29 mg/dL and CRP > 140.5 mg/L increased the risk of mortality 3.9-fold, 9.4-fold, 4.3-fold and 4.1-fold, respectively." (PMID 35160110, 2022). "Finally, increasing LDL cholesterol concentration and improving HDL cholesterol efflux have been shown to improve C-reactive protein (CRP) associated inflammation in diseases such as rheumatoid arthritis." (PMID 36131046, 2022). "An observational study showed that baseline CRP levels predicted long-term interstitial lung disease progression, and another found that high-positive CRP was associated with rheumatoid arthritis-associated interstitial lung disease, which also conflicts with our causal evidence." (PMID 34386016, 2021). "A similar explanation probably underlies the apparent association between the CRP genome-wide allele score and the auto-immune diseases except the mediating variable is likely to be some immune parameter that affects both CRP and risk of rheumatoid arthritis/type I diabetes/Crohn's disease." (PMID 24204319, 2013). "While CRP levels are typically low in healthy individuals, the level of this protein can increase significantly in the presence of inflammation, making it a widely used and valuable diagnostic biomarker for e.g., inflammatory diseases such as rheumatoid arthritis (RA), and bacterial infections." (PMID 37724104, 2023).
rheumatoid arthritis (continued). "In a randomized controlled trial (RCT) of patients with rheumatoid arthritis, fasting was associated with improvement in symptoms of inflammation such as swelling and pain and inflammatory markers, namely, erythrocyte sedimentation rate, C-reactive protein level, and white blood cell count." (PMID 37043764, 2023). "For example, in rheumatoid arthritis (RA), IL-6 is produced locally in the joints, causing joint swelling and elevated C-reactive protein." (PMID 35956246, 2022). "High levels of C-reactive protein (CRP) have been associated with inflammation in the TMJ in patients with rheumatoid arthritis (RA)." (PMID 31687055, 2019). "In patients with rheumatoid arthritis (RA), a prospectively study also demonstrated that higher average CRP levels are associated with incident or progressive plaque, but only in patients with high CVD risk." (PMID 25890227, 2015). "Again this observation may indicate an active or causative role for CRP in rheumatoid arthritis." (PMID 24799767, 2014). "Therefore, this study aimed to determine whether CRP gene variants could also influence CRP serum levels in rheumatoid arthritis." (PMID 20877716, 2010). "Proteomic analyses identify CRP as a core inflammatory mediator in conditions such as rheumatoid arthritis, while single-cell RNA sequencing delineates its major cellular sources." (PMID 42199431, 2026). "To distinguish the similarity of the Spry1-cKO joint phenotype with PsA from rheumatoid arthritis, we examined C-reactive protein (CRP) and rheumatoid factor levels in Spry1-cKO mice plasma." (PMID 40471688, 2025). "It has an anti-inflammatory effect, as was demonstrated by a decrease in the CRP levels in rheumatoid arthritis patients." (PMID 40136507, 2025). "Further complicating the diagnosis were early laboratory findings such as elevated RF and CRP, which misleadingly suggested autoimmune pathology such as early rheumatoid arthritis." (PMID 41282378, 2025). "MTX has been shown to reduce CRP levels in inflammatory conditions characterized by elevated CRP, such as rheumatoid arthritis." (PMID 41375637, 2025). "The hsa-mir-335-5p is widely expressed in human and has been found to positively correlate with anti-CCP antibodies and C-reactive protein in rheumatoid arthritis (RA), and is a good biomarker for RA." (PMID 40438384, 2025). "Several studies have pointed to the relationship between above-average CRP levels and autoimmune diseases such as rheumatoid arthritis and SLE." (PMID 41259457, 2025). "Relying on CRP as a sole inflammatory marker has been shown to lead to severe infections being overlooked in patients with rheumatoid arthritis under tocilizumab treatment." (PMID 39210228, 2025). "Elevated CRP levels are common in autoimmune conditions such as systemic lupus erythematosus and rheumatoid arthritis, where chronic inflammation can extend beyond peripheral tissues to impact the central nervous system (CNS)." (PMID 41373439, 2025). "In another study, the daily oral administration of sesamin for 6 weeks improved the number of tender joints in patients with rheumatoid arthritis through reductions in serum levels of C reactive protein, TNF-α, and cyclooxygenase-2." (PMID 40142993, 2025). "It has been reported that among patients with rheumatoid arthritis (n = 41) after 12 weeks of treatment with the live attenuated vaccine, CRP and ESR levels remained unchanged." (PMID 40006724, 2025). "Similarly, the Brigham and Women’s Rheumatoid Arthritis Sequential Study (BRASS), an RA-specific cohort, reported associations between higher systemic inflammation (including total CRP) and subjective cognitive complaints." (PMID 40943152, 2025). "In patients with rheumatoid arthritis, rituximab significantly reduced serum concentrations of CRP, RF, anti-CCP, IL-2, IL-6, IL-7, IL-10, and ESR." (PMID 41057909, 2025).